PAK3 (p21 (RAC1) activated kinase 3)
Diseases named in the same sentence as PAK3 in open-access papers (continued):
Sharing a sentence is not in itself a finding about the gene and the disease.
tumor (13 papers, 2013 to 2025). "Among the 130 up-regulated genes, those encoding E-cadherin, MAPK10, MAP3K5, and PAK3 have been confirmed to inhibit tumor proliferation or invasion." (PMID 28454092, 2017). "To understand the mechanisms by which PAK3 affects tumor formation, invasion, and metastasis as well as EMT in HCC cells, we next examined molecules involved in the relevant pathways." (PMID 34976179, 2022). "Functional experiments showed that PAK3 was closely related to tumor proliferation, metastasis and invasion." (PMID 34976179, 2022). "In this study, our finding that Smad4 inactivates the PAK3-JNK-Jun pathway in advanced or metastatic lung cancer provides a function for the tumor-suppressive Smad4." (PMID 34381046, 2021). "We also found that circ_0000190 overexpression led to decrease in miR-132 level and increase in PAK3 protein expression of tumor xenograft." (PMID 32742198, 2020). "MiR-1252 and PAK3 were significantly increased and decreased in tumor tissues, respectively." (PMID 32742198, 2020). "Many of these genes, including those encoding bFGF, MAPK10, MAP3K5, IL1R2, E-cadherin, Ki67, Cyclin E1, beta-catenin, 14-3-3 protein T-cell (YWHAQ), integrin alpha-V (ITGAV), integrin alpha-10 (ITGA10), CDK6, PCNA, CDKN1A, and PAK3, are related to tumor metastasis and regulation of cell migration." (PMID 28454092, 2017). "Our data provides a comprehensive comparison of DepMap dependency scores for PAK1, PAK2, PAK3, PAK4, PAK5, and PAK6, based on CRISPR analysis of 1100 tumor cell lines and RNAi analysis of 711 cell lines." (PMID 39756822, 2025). "With regarded to PAK3, in three types of tumors, including LGG, GBM, and SARC, samples, the number of infiltrating tumor cells was higher than that of low expression samples, which was contrary to most other tumors." (PMID 36064705, 2022). "In addition, due to the lack of PAK7 data in the GSVA database, we grouped 28 tumor patients according to the methylation status of PAK1, PAK2, PAK3, PAK4, and PAK6, respectively, and then analyzed the survival difference of tumor patients." (PMID 36064705, 2022). "However, SPK mice injected with miR-495 mimics resulted in no tumor metastasis accompanied by reduced PAK3, p-JNK, and p-Jun levels in tumors." (PMID 34381046, 2021).
neurodevelopmental disorder (4 papers, 2020 to 2025). A behavioral and cognitive disorder with onset during the developmental period that involves impaired or aberrant development of intellectual, motor, or social functions. "Our findings are consistent with a small number of previous studies (reviewed in2) reporting PAK3 pathogenic variants in families with X‐linked neurodevelopmental disorder." (PMID 39806575, 2025). "Recent genetic evidence highlight that the Rac/Cdc42 pathway of which PAK3 is part plays a major role in brain development and functions and its mutational dysfunction leads to neurodevelopmental disorder." (PMID 39806575, 2025). "P21-activated kinase 3 (PAK3) gene mutations are linked to several neurodevelopmental disorders, but the underlying mechanisms remain unclear." (PMID 34831234, 2021). "We describe an Italian family with a female individual without neurodevelopmental disorder who is mosaic for a novel, rare PAK3 pathogenic variant." (PMID 39806575, 2025). "However, reported electro‐clinical features of PAK1‐associated neurodevelopmental disorder are distinct from those in PAK3 neurodevelopmental disorder including multi‐focal spike wave and epileptic discharges, and sharp waves in frontal and temporal regions." (PMID 39806575, 2025). "We confirm craniofacial abnormalities even in a mosaic female without neurodevelopmental disorder, further delineating the PAK3‐related phenotype and informing genetic counseling for her adult affected sons." (PMID 39806575, 2025).
infection (2 papers, 2015 to 2021). The state of being infected such as from the introduction of a foreign agent such as serum, vaccine, antigenic substance or organism. "A significant knockdown of PAK3 mRNA was observed in HeLa cells after infection with each of the four tested shRNAs." (PMID 25615606, 2015). "A time course of caspase 3/7 expression induced by the various PAK3 shRNAs indicated peak expression 72 hours after infection (time course data not shown)." (PMID 25615606, 2015).
mental illnesses (2 papers, 2022 to 2023). "Pathogenic variations of PAK1, PAK2 and PAK3 are responsible for ID and/or psychiatric disorders, and are often associated with brain anomalies." (PMID 36937657, 2023). "Transcriptomic analysis and genome-wide association in schizophrenia and bipolar disorder identify PAK1 and PAK3 as the differentially expressed genes along with several other genes in the RAC1/CDC42 pathway, highlighting the role of this pathway in these psychiatric disorders." (PMID 36937657, 2023).
neurological diseases (2 papers, 2021 to 2024). "The genes with the highest number of connections with other diseases were PAK3, GRIA3, and ADGRB1 associated with eight, six, and six neurological diseases, respectively." (PMID 33922640, 2021).
neurodegenerative disease (1 paper, 2015). A disorder of the central nervous system characterized by gradual and progressive loss of neural tissue and neurologic function. "In addition, reduced expression levels in the elderly were found for the PAK1 and PAK3 genes, which play a crucial role in neuronal cell fate, polarization, and migration and are implicated in neurodegenerative diseases." (PMID 25977747, 2015).
PAK3 also shares sentences with these, for which no sentence is quoted: psychosis (2 papers); X-linked intellectual disability (2); Anxiety (1); behavioral disorders (1); brain disease (1); breast carcinoma (1); cognitive disorder (1); colon cancer (1); corpus callosum agenesis (1); Dent disease (1); Granuloma (1); head and neck cancer (1); heart failure (1); Huntington disease (1); hypertrophic cardiomyopathy (1); malaria (1); metastatic cancers (1); Obesity (1); osteosarcoma (1); prostate adenocarcinoma (1); sleep (1); sleep disorder (1).